LCN2 (lipocalin 2)
Diseases named in the same sentence as LCN2 in open-access papers (continued):
Sharing a sentence is not in itself a finding about the gene and the disease.
Hepatic steatosis (19 papers, 2016 to 2025). Steatosis is a term used to denote lipid accumulation within hepatocytes. "Recently, XU and colleagues found that LCN2 overexpression within mouse hepatocytes protected from diet-induced liver steatosis, and LCN2-deficient mice presented the opposite phenotype." (PMID 35034646, 2022). "Another study used HFD and methionine-/choline-deficient diet for inducing hepatic steatosis and steatohepatitis and found that LCN2−/− mice accumulated more hepatic lipids in both two models." (PMID 35034646, 2022). "We previously reported that hepatic Lcn2 overexpression, and increased circulating levels of LCN2 are associated with hepatic steatosis and insulinemia in DIO." (PMID 31892368, 2019). "Our results indicate that elevated hepatic LCN2 and IL-1β are closely associated with hepatic insulin impairment, hepatic steatosis, and excessive lipid circulation, consistent with previous reports." (PMID 31892368, 2019). "The data presented in this brief report support the research article “Altered mitochondrial and peroxisomal integrity in lipocalin-2-deficient mice with hepatic steatosis” [1, doi: 10.1016/j.bbadis.2017.04.006]." (PMID 28725667, 2017). "In addition to its tissue direct effects on IR, TNF regulates pro-inflammatory markers, such as IL-6 and lipocalin-2 (LCN2) that are implicated in the pathogenesis of hepatic steatosis and T2D onset and progression." (PMID 31892368, 2019). "Furthermore, the authors found that LCN2 level had a positive association with hepatic steatosis." (PMID 35034646, 2022). "In the present study, studying the potential role of LCN2 in CCl4-treated ob/ob mice can provide valuable insights into the pathophysiology of fatty liver and subsequent progression to hepatic fibrosis and can help to identify potential therapeutic targets." (PMID 39832399, 2025). "Our previous studies have revealed that caloric restriction reduced increased LCN2 levels in genetic ob/ob and db/db mice with hepatic steatosis." (PMID 35884685, 2022). "The authors performed Pearson’s correlation for investigating the relationship between decrease in LCN2 levels and hepatic steatosis improvement." (PMID 35034646, 2022). "Two genes were found highly significantly regulated: Lcn2, a potential biomarker for hepatic steatosis, damage, and inflammation, and Resf1, a factor regulator of epigenetics modification associated with SETDB1." (PMID 35327511, 2022). "To investigate the protective effects of ABE on inflammation and oxidative stress in hepatic steatosis, we examined hepatic LCN2, HO-1, and SOD1 expressions." (PMID 36501079, 2022). "The authors also investigated the relationship between alterations in LCN2 levels and hepatic steatosis improvement after LSG." (PMID 35034646, 2022). "In conclusion, this study revealed that circulating LCN2 levels were increased among patients with higher BMI and more severe hepatic steatosis." (PMID 35034646, 2022). "The decrease in LCN2 was positively correlated with the hepatic steatosis improvement after age, gender, and the decrease in BMI were adjusted." (PMID 35034646, 2022). "Taken together, these findings indicate that LCN2 deletion could attenuate hepatic steatosis and inflammation in diabetic mice." (PMID 35884685, 2022). "Taken together, these results suggest that ABE may have a protective role in inflammation and oxidative stress in HFD-induced hepatic steatosis by downregulating LCN2 production." (PMID 36501079, 2022). "However, the results from different studies were inconsistent and the relationship between LCN2 levels and hepatic steatosis is still unclear." (PMID 35034646, 2022). "In addition to its elevation in NAFLD, the current study also demonstrated that LCN2 levels were correlated with steatosis grade and that the decrease in circulating LCN2 levels was correlated with the improvement in hepatic steatosis after bariatric surgery." (PMID 35034646, 2022).
Hepatic steatosis (continued). "Circulating LCN2 levels may be a biomarker for hepatic steatosis severity and be monitored during the follow-up of NAFLD treatment in the future." (PMID 35034646, 2022). "Lcn2 has shown a sex specific difference in hepatic steatosis in a mice study." (PMID 34327512, 2021). "Additionally, we are the first to demonstrate that selective solTNF signaling with XPro can regulate the hepatic and intestinal LCN2 levels in the presence of hepatic steatosis and metabolic inflammation in DIO." (PMID 31892368, 2019). "Furthermore, compared to WT animals, LCN2 KO mice develop more hepatic steatosis after fructose treatment." (PMID 29234288, 2017). "The decreased serum LCN2 levels could be an indicator of hepatic steatosis improvement." (PMID 35034646, 2022). "Finally, this study only showed an association between circulating LCN2 levels and hepatic steatosis, the causal relationship was not explained." (PMID 35034646, 2022). "Next, we investigated whether LCN2 deletion attenuated hepatic steatosis in diabetic mice." (PMID 35884685, 2022). "Here, we show that both DL- and NDL-PCBs induce hepatic steatosis, fibrosis, inflammation and HIO by upregulating the expression of hepatic LCN2, resulting in the induction of NAFLD/NASH in vivo and in vitro." (PMID 36012166, 2022). "For most studies, LCN2 levels were elevated in NAFLD and found to be correlated with hepatic steatosis." (PMID 35034646, 2022). "In the present study, the knockdown of hepatic NCN2 using a siRNA delivery system resulted in improvement in PCB-induced hepatic steatosis and HIO in vitro models, indicating that LCN2 plays a critical role in PCB-induced NAFLD/NASH." (PMID 36012166, 2022). "The present study focused on analyzing serum LCN2 levels of obese patients with nonalcoholic fatty liver disease (NAFLD) and on determining relationship of hepatic steatosis improvement with LCN2 levels after laparoscopic sleeve gastrectomy (LSG)." (PMID 35034646, 2022). "Thus, both LCN2 and PLIN5 affect energy and fat metabolism in a manner related to insulin sensitivity, and both seem to be pivotal in hepatic steatosis and inflammation because of their hepatoprotective functions." (PMID 29234288, 2017). "Given that an acute-phage protein LCN2 serves as a marker of liver damage, we propose that levels of hepatic enzymes and LCN2 may not help effectively differentiate between hepatic steatosis and fibrosis." (PMID 39832399, 2025).
liver fibrosis (19 papers, 2014 to 2025). "In a previous study, LCN2 deficiency was shown to protect against HFD‐induced liver fibrosis in ob/ob mice." (PMID 38622198, 2024). "The authors found that hepatic expression of Col1a1 was elevated in ASH patients and correlated with hepatic LCN2 expression, and Lcn2-deficient mice were protected from liver fibrosis caused by either ethanol or CCl4 exposure." (PMID 34675931, 2021). "We identified a PPI network module associated with liver fibrosis that includes known liver fibrosis-relevant genes, such as tissue inhibitor of metalloproteinase-1, galectin-3, connective tissue growth factor, and lipocalin-2." (PMID 25380136, 2014). "We identified a PPI network module associated with liver fibrosis that includes known liver fibrosis-relevant genes like Timp1, Lgals3, Ctgf, and Lcn2, along with several new genes." (PMID 25380136, 2014). "Notably, LCN2 was also shown to be upregulated in ductular reactive cells during CCl4-induced liver fibrosis model and in the NASH model induced by Choline-Deficient L-Amino Acid-Defined High-Fat Diet (CDAHFD)." (PMID 37784089, 2023). "In conclusion, we demonstrate that CCl4-induced hepatic fibrosis was closely associated with hepatic inflammation, oxidative stress, apoptosis, and autophagy, but these adverse effects were less severe in leptin-deficient ob/ob mice than in WT mice through downregulating LCN2-related signaling." (PMID 39832399, 2025). "In our previous study, we demonstrated that lipocalin-2 (LCN2) promotes hepatic fibrosis in high-fat diet (HFD)-fed ob/ob mice by activating HSCs." (PMID 39832399, 2025). "Beyond cancer, LCN2 is associated with fibrosis, where it correlates with COL1A1 expression and drives ECM remodeling in liver fibrosis." (PMID 40472740, 2025). "Given that LCN2 promoted hepatic fibrosis, we measured LCN2 protein levels in the serum, epididymal fat pads, and liver." (PMID 39832399, 2025). "To additionally validate the effect of LCN2 on hepatic fibrosis, we assessed hepatic α-SMA expression in CCl4-treated WT, ob/ob, and LCN2KO mice." (PMID 39832399, 2025). "LCN2 gene expression and secretion increased in CCl4-induced liver fibrosis mice model, and SREBP-1c regulated LCN2 gene transcription." (PMID 38622198, 2024). "Histologically, the progression of liver fibrosis was lower in the HFD-fed (20 week-old) LCN2 KO mice than in HFD-fed WT mice, and similar changes in the expression of α-SMA were observed." (PMID 38622198, 2024). "Taken together, these results suggest that SREBP-1c drives liver fibrosis and that LCN2 is a direct target of SREBP-1c." (PMID 38622198, 2024). "Overall, this study confirmed that decreasing LCN2 ameliorated liver fibrosis by regulating intracellular iron levels in HSCs." (PMID 38622198, 2024). "In this study, we investigated the role of SREBP-1c in regulating LCN2 expression in the liver, which contributes to iron-induced liver fibrosis and NASH." (PMID 38622198, 2024). "This study demonstrated that LCN2 level was correlated with the severity of liver inflammation and the stage of hepatic fibrosis, making it a good candidate biomarker or even a therapeutic target for NAFLD and fibrosis." (PMID 37784089, 2023). "Given that LCN2 is associated with hepatic fibrosis in HFD-fed ob/ob mice, we examined the effects of IF on the LCN2-related signaling pathway in HFD-fed mice." (PMID 37960230, 2023). "Analysis of clinical samples from patients with liver fibrosis also showed a huge abundance of endogenous CD24+LCN2+ cells in ductular reaction foci." (PMID 37784089, 2023). "HSC activation-induced MMP9 production plays an important role in hepatic fibrosis through LCN2/STAT3-mediated signaling." (PMID 37960230, 2023). "The splenectomy mice showed enhanced liver fibrosis and inflammation, accompanying significantly decreased Lcn2 in portal vein." (PMID 36052075, 2022).
liver fibrosis (continued). "To overcome this limitation, we assessed the functional role of LCN2 in human samples and in mice subjected to a well characterized model of liver fibrosis." (PMID 32968110, 2020). "To further study the role of LCN2 in liver fibrosis, we used CCl4 for 4 weeks to induce advanced fibrosis in WT and Lcn2-/– mice." (PMID 32968110, 2020). "On the other hand, to determine whether LCN2 affects iron accumulation in CCl4-induced hepatic fibrosis, we performed Perls Prussian blue iron staining." (PMID 39832399, 2025). "LCN2 expression is markedly elevated in liver fibrosis models, suggesting its role in fibrogenesis." (PMID 39832399, 2025). "Thus far, our data support a model in which HFHS increases SREBP-1c-mediated LCN2 activation in hepatocytes and in which the secreted protein drives HSC-mediated liver fibrosis through the direct binding of holo-LCN2 to HSCs." (PMID 38622198, 2024). "In conclusion, Wfdc21, Lcn2, Pglyrp1, and Mmp8 may be potential and novel neutrophil targets to decrease liver fibrosis." (PMID 39040848, 2024). "Interestingly, LCN2 had higher expression in the CDAHFD diet-induced NASH model than in the CCl4-induced liver fibrosis model according to our PCR data." (PMID 37784089, 2023). "These excessively high levels of hepatocytes-derived LCN2 in NASH model might hamper investigating the roles of LPCs-derived LCN2 against hepatic fibrosis as compared to the CCl4 model." (PMID 37784089, 2023). "Taken together, the downregulation of LCN2 in activated HSCs may alleviate the progression of liver fibrosis." (PMID 36655094, 2023). "The splenic Lcn2 might have an important role in regulating hepatic immune tolerance during the development of liver fibrosis." (PMID 36052075, 2022). "The Lcn2 null mice developed less inflammation due to defects in genes involved in the myeloid cell activation process, and downregulated gene sets for collagen-containing extracellular matrix leading to mitigation of the liver fibrosis." (PMID 34518636, 2021). "Lcn2 null mice develop less inflammation due to defective genes involved in myeloid cell activation, and downregulated gene sets for collagen-containing extracellular matrix, leading to mitigation of the liver fibrosis." (PMID 34518636, 2021). "The ability of hepatocyte regeneration combined with lower leukocyte inflammatory responses might promote tissue repair and attenuate liver fibrosis in Lcn2–/– mice." (PMID 34518636, 2021). "We hypothesized that LCN2 secretion may impact liver fibrosis." (PMID 34616693, 2021). "In line with our finding that IF reduces hepatic LCN2, MMP9, and pSTAT3 expression in HFD-fed mice, LCN2 deletion and administration of a STAT3 phosphorylation inhibitor reduced inflammation and hepatic fibrosis." (PMID 37960230, 2023). "Therefore, targeting LCN2 might improve liver fibrosis by regulating ferroptosis." (PMID 36655094, 2023). "In LD mouse model, Lcn2 exacerbated the development of ALD, and Lcn2 knockout protected mice from ALD and liver fibrosis." (PMID 34327512, 2021). "The genes labeled as Lcn2, ColIα1, MMp12, and Dbp were upregulated, while Aox4, Cyp2c11, Mup5, LOC100912565, LOC100909412, LOC100360095, and LOC259244 were downregulated in the process of liver fibrosis." (PMID 34597331, 2021). "Their results show correlation of LCN2 to liver damage and resulting inflammatory responses but not to the degree of liver fibrosis." (PMID 33826640, 2021). "Other studies show no direct correlation between LCN2 and hepatic fibrosis." (PMID 33826640, 2021). "In a subsequent study, that included a total of n = 192 patients with chronic liver diseases of any etiology and healthy controls showed that LCN2 is a reliable indicator of liver damage that is positively correlated with inflammation, but is not correlated with the degree of liver fibrosis per se." (PMID 27729871, 2016).
liver fibrosis (continued). "Meanwhile, further studies are necessary to establish whether CD24+LCN2+ LPCs, a major LPC type in ductular reaction, have a ‘reprogramming competence’ to reduce hepatocyte and biliary epithelial cell plasticity (like hepPDs and TLPC) during liver fibrosis and NASH." (PMID 37784089, 2023).
asthma (18 papers, 2015 to 2026). "The gelatinase-bound protein lipocalin-2 (NGAL) is associated with the degree of respiratory obstruction in asthma and can induce ASM cell proliferation." (PMID 36359743, 2022). "Consequently, the Fra2/LCN2 axis may represent a potential therapeutic target for environment-associated asthma." (PMID 42214888, 2026). "This study identifies a novel pathway by which PM2.5 promotes asthma pathogenesis by activating the Fos-related antigen 2 (Fra2)/Lipocalin 2 (LCN2) axis, thereby inducing ferroptosis in M2 macrophages." (PMID 42214888, 2026). "Collectively, these findings reveal a previously unrecognized mechanism whereby PM2.5 exacerbates asthma through Fra2/LCN2-mediated mitophagy dysfunction and ferroptosis in M2 macrophages." (PMID 42214888, 2026). "This study aimed to investigate the association between serum levels of lipocalin-2 (LCN2), soluble suppression of tumorigenicity 2 (sST2), and fibroblast growth factor 21 (FGF21) with asthma severity and to evaluate their predictive value for prognosis." (PMID 41230779, 2025). "Based on this, we can judge the contribution of lipocalin-2 to the development of bronchial hyperreactivity." (PMID 36291711, 2022). "Lipocalin-2 is also elevated in the respiratory secretions of horses with severe asthma and is further increased in lung tissue after an antigenic exposure." (PMID 36359743, 2022). "Our observation that nasal HNP1-3 and LCN2 were significantly lower in the asthma patients is in line with observations in previous studies showing lower AMP levels in allergy." (PMID 26545199, 2015). "and higher LCN2 in nasal secretions during the pollen season in asthma compared to controls." (PMID 26545199, 2015). "Other studies reported higher sputum LCN2 levels in asthma patients compared to controls." (PMID 26545199, 2015). "Serum LCN2, sST2, and FGF21 levels increase with asthma severity and demonstrate high predictive value for poor prognosis when combined." (PMID 41230779, 2025).
end-stage renal disease (18 papers, 2010 to 2024). "Additionally, it has been found that lipocalin-2 was highly expressed in patients with end-stage renal failure." (PMID 38178854, 2024).
endotoxemia (18 papers, 2010 to 2025). "Together with the findings from ISH, these results indicated that the predominant Lcn2 producer cells in the CNS of mice with LPS-induced endotoxemia are endothelial cells, choroid plexus-associated cells and microglia." (PMID 21943033, 2011). "Here we employed Lcn2 KO mice to determine if Lcn2 played a role in the cerebral host response to LPS-induced endotoxemia." (PMID 21943033, 2011). "Therefore, here we investigated the expression and localization of Lcn2 RNA and protein, as well as 24p3R RNA, in the brain in a model for systemic LPS-induced endotoxemia." (PMID 21943033, 2011). "To determine further whether Lcn2 may contribute to glial activation in response to LPS-induced endotoxemia we performed immunohistochemical analysis of brain sections." (PMID 21943033, 2011). "Treatment of Lcn2-deficient mice with the iron chelator desferrioxamine leads to protection from bacteria-free endotoxemia, suggesting an alternate role for LCN2 in the innate immune response to Gram-negative bacteria outside of its role in siderophore sequestration." (PMID 36054235, 2022).